ERC1 (ELKS/RAB6-interacting/CAST family member 1)
Description:
Regulatory subunit of the IKK complex. Probably recruits IkappaBalpha/NFKBIA to the complex. May be involved in the organization of the cytomatrix at the nerve terminals active zone (CAZ) which regulates neurotransmitter release. May be involved in vesicle trafficking at the CAZ. May be involved in Rab-6 regulated endosomes to Golgi transport.
Synonyms: ERC-1; ELKS; KIAA1081; RAB6IP2; CAST2; MGC12974
Tractability: Antibody: UniProt places it where antibodies can reach, with medium confidence; its Gene Ontology location is reachable by antibodies, with medium confidence; the Human Protein Atlas places it where antibodies can reach. PROTAC: ubiquitination databases record sites on it; its protein half-life has been measured.
Gene: Protein-coding gene on chromosome 12 (989,998 to 1,495,933, forward strand). Ensembl gene ENSG00000082805.
Subcellular location: Cytoplasm, cytoskeleton, microtubule organizing center, centrosome; Cytoplasm; Membrane; Golgi apparatus membrane; Presynaptic cell membrane; Cell projection, podosome
Subcellular location (Human Protein Atlas): Plasma membrane; Centrosome; Vesicles
Gene Ontology:
Molecular function: cadherin binding; protein binding; PDZ domain binding; small GTPase binding; structural constituent of presynaptic active zone
Biological process: positive regulation of canonical NF-kappaB signal transduction; regulation of DNA-templated transcription; establishment or maintenance of cell polarity; maintenance of presynaptic active zone structure; retrograde transport, endosome to Golgi
Cellular component: centrosome; ciliary basal body; cytoplasm; IkappaB kinase complex; cell cortex; microtubule associated complex; podosome; presynaptic active zone cytoplasmic component; presynaptic membrane; synapse; Golgi membrane; membrane; presynapse
Genetic constraint (gnomAD): Loss-of-function variants: 45 observed, 114.68 expected, observed/expected ratio (o/e) 0.39, 90% interval 0.31 to 0.5. The upper end of that interval is the gene's LOEUF score, 0.5, which puts it in group 2 of 6, group 1 being the genes least tolerant of losing a copy. Missense variants: 1,097 observed, 1,300.4 expected, observed/expected ratio (o/e) 0.84, 90% interval 0.8 to 0.89. Synonymous variants: 434 observed, 461.07 expected, observed/expected ratio (o/e) 0.94, 90% interval 0.87 to 1.02.
Homologues: Orthologues: macaque ERC1 (99% identical), chimpanzee ERC1 (99% identical), dog ERC1 (99% identical), rabbit ERC1 (98% identical), guinea pig ERC1 (98% identical), rat Erc1 (97% identical), mouse Erc1 (97% identical), pig ERC1 (95% identical), tropical clawed frog erc1 (87% identical), zebrafish ERC1 (82% identical), zebrafish erc1a (66% identical), Caenorhabditis elegans elks-1 (22% identical), and 1 more. Paralogues in human: ERC2 (62% identical).
Diseases named in the same sentence as ERC1 in open-access papers:
ERC1 is named in the same sentence as 45 diseases in open-access papers, as found by Europe PMC text mining. Sharing a sentence is not in itself a finding about the gene and the disease. The quoted sentences say what the papers report.
papillary thyroid carcinoma (4 papers, 2012 to 2025). "RET fusions (involving CCDC6, PRKAR1A, NCOA4 (ELE1), GOLGA5, TRIM24 (HTIF1), TRIM33 (RFG7), and KTN1 and ERC1 (ELKS)) are found in papillary thyroid cancers." (PMID 22928112, 2012).
autism spectrum disorder (3 papers, 2016 to 2023). A spectrum of developmental disorders that includes autism, and Asperger syndrome. "Human genetic experiments reveal that mutations in ERC1/ELKS1 may contribute to autism spectrum disorders, and it is possible that the pathophysiology arises from synapse-specific misregulation of neurotransmitter release." (PMID 27253063, 2016).
breast carcinoma (3 papers, 2014 to 2024). "In addition, we detected previously identified RET fusions in new tumour indications, including a single CCDC6–RET fusion in colon adenocarcinoma and a single ERC1–RET fusion in breast cancer." (PMID 25204415, 2014).
autism (2 papers, 2023 to 2024). Persistent deficits in social interaction and communication and interaction as well as a markedly restricted repertoire of activity and interest as well as repetitive patterns of behavior. "Both these genes are associated with neurological diseases; (ERC1 with pontocerebellar hypoplasia type 2E and CNTNAP2 with Pitt–Hopkins-Like syndrome 1 and autism 1528)." (PMID 36774368, 2023).
colorectal cancer (2 papers, 2021 to 2023). A primary or metastatic malignant neoplasm that affects the colon or rectum. "DSVs in SGSM2 and LHFPL3 were relevant to colorectal cancer, whereas ADAP1, DLGAP2, ERC1, and PPP6R2 were related to gynecologic cancer." (PMID 33431054, 2021). "In the “Other tumors group” four rearrangements involving BRAF gene were detected (three melanoma: BRAF::CNNM2, BRAF::ERC1, BRAF::MAD1L1 and one pancreatic adenocarcinoma BRAF::SND1), but also one ETV6::NTRK3 (colorectal cancer) and one FGFR3::TACC3 (urothelial cancer)." (PMID 37708140, 2023).
HCMV infection (2 papers, 2015 to 2018). "Previous studies have shown that ATM signaling is required for efficient HCMV replication, and knockdown of ATM resulted in a similar phenotype as knockdown of ERC1 in our screen, supporting a role for ERC1 in proviral DNA damage signaling during HCMV infection." (PMID 29946045, 2018). "Since it is known that ATM is activated during HCMV infection, targeted degradation of ERC1 could serve as an elegant way to antagonize innate immunity response through attenuation of NF-κB signaling." (PMID 26599541, 2015). "We conducted simultaneous real-time PCR and western blot analysis on cell extracts along HCMV infection and could confirm profiles that suggest active degradation of ROCK1 and ERC1." (PMID 26599541, 2015).
apraxia of (1 paper, 2023). "A recent genotype–phenotype characterization proposed ERC1/ELSKS as a good candidate gene for childhood apraxia of speech (CAS)." (PMID 37422671, 2023).
invasive breast carcinoma (1 paper, 2023). A carcinoma that infiltrates the breast parenchyma. "Fusions of either LL5β or ERC1 with different genes including tyrosine kinase receptors (e.g. ERC1-RET) have been identified in invasive breast cancer and other tumors (cBioPortal, TCGA)." (PMID 37437062, 2023).
myopia (1 paper, 2016). "Among the mRNAs targeted by differentially expressed miRNAs, there were several (Prkar1a, Rims2, Map2, Gabarapl1, Htr7, Add3, Erc1, Nlgn1) which were involved in synapse formation and function suggesting that synaptic function was one of the biological processes affected in form-deprivation myopia." (PMID 27622715, 2016).
sarcoma (1 paper, 2025). A usually aggressive malignant neoplasm of the soft tissue or bone. "In turn, ERC1-ALK fusions have been seen in sarcomas and non–small cell lung carcinoma." (PMID 40016412, 2025).
Sepsis (1 paper, 2020). Sepsis is defined as life-threatening organ dysfunction caused by a dysregulated host response to infection. "Of the 317 sepsis-associated genes regulated by these DEMs, five (HIP1, GJC1, MDM4, IL6R, and ERC1) were designated as hub genes based on their degrees and other centrality measures (degree, betweenness, and closeness) from the significant modules." (PMID 33182754, 2020).
testis cancer (1 paper, 2024). "Almost all of the top-performing genes were that of over-expression, with PMS2 in THYM; CARD11, LASP1, STIL, POLE, KMT2C, and CLIP1 in testis cancer; ERC1, WRN, OLIG2, FANCC, and ACSL6 in ACC; and SOX2 and NDRG1 in ESCA leading in performance with AUCs ranging 0.832-0.911." (PMID 38491101, 2024).
tumor (11 papers, 2014 to 2026). "The scaffold protein LL5β interacts with the scaffold ERC1, and recruits it at plasma membrane–associated platforms that form at the front of migrating tumor cells." (PMID 37437062, 2023). "We have recently proposed a model in which liprin-α1 and ERC1 are part of dynamic plasma membrane–associated platforms (PMAPs) important for the polarized migration of tumor cells during invasion." (PMID 27659488, 2016). "Similar to liprin-α1 or ERC1 silencing, expression of the liprin-N negatively affects tumor cell motility and extracellular matrix invasion, acting as a dominant negative by interacting with endogenous liprin-α1 and causing the displacement of the endogenous ERC1 protein from the cell edge." (PMID 27659488, 2016). "LL5 and ERC1 proteins support protrusion during migration as shown by the finding that depletion of either endogenous protein impairs tumor cell motility and invasion." (PMID 37437062, 2023). "In cells liprin-α1 is part of a network of scaffold and signaling proteins including the ERC1/ELKS, LL5 adaptors that form dynamic plasma membrane-associated platforms (PMAPs) near the edge of migrating tumor cells." (PMID 36171301, 2022). "Liprin-α1 and ERC1 are interacting scaffold proteins regulating the motility of normal and tumor cells." (PMID 27659488, 2016). "Interestingly, there was a consistent kataegis on chromosome 12 ERC1 gene in the upper microniches of the tumor." (PMID 37644058, 2023). "In this study we have tested the hypothesis that interfering with the interaction between LL5β and ERC1 may be used to interfere with the function of the endogenous proteins to inhibit tumor cell migration." (PMID 37437062, 2023). "Moreover, expression of either fragment is able to specifically delocalize endogenous ERC1 from the edge of migrating MDA-MB-231 tumor cells." (PMID 37437062, 2023). "ERC1/LL5 proteins are part of the PMAPs machinery that regulates tumor cell invasion." (PMID 37437062, 2023). "Interfering with the formation of proper liprin-α1 homo-complexes and with the localization of ERC1 may represent efficient ways to interfere with cell migration, and with invasive tumor cell motility in particular." (PMID 27659488, 2016). "This hypothesis was supported by the observation that the expression of the liprin-N fragment inhibited tumor cell motility and invasion, as previously shown after knocking down either liprin-α1 or one of its functional partners ERC1 and LL510." (PMID 27659488, 2016). "A young adult with upfront nephrectomy had a difficult-to-classify tumour; WGS revealed a novel ERC1-CCNY fusion as a likely novel driver event." (PMID 41933220, 2026). "Liprin-α1 together with ERC1/ELKS and LL5 proteins (LL5α and -β) regulate focal adhesion turnover and lamellipodial dynamics near the protruding tumor cell edge, where these proteins are part of dynamic plasma membrane-associated platforms (PMAPs)." (PMID 34654889, 2021). "Establishment of native tumor cell lines with other RET-fusions, including TRIM33-RET, CLIP1-RET, and ERC1-RET, is also warranted." (PMID 29088743, 2017). "Recurrent SVs in CSMD1, WWOX, ERC1, PDE4D and SHANK2 were also identified in five tumor samples." (PMID 32617189, 2020). "However, some of these and other potential alternative driver genes identified in wildtype tumours such as KMT2A, FANCC and ERC1 were also identified in many of the RAS/RAF mutant cases." (PMID 26506417, 2015). "Additional amplification of WT1, ERC1, ASIC2 and MTCP1 and deletion of CDKN2A and MLLT3 were found in recurring MFS (case 8b) but not in the original tumor (case 8a)." (PMID 38791144, 2024).
cancer (6 papers, 2018 to 2024). A tumor composed of atypical neoplastic, often pleomorphic cells that invade other tissues. "Of note, liprin-α1 affects cancer cell spreading, the distribution of cell surface β1-integrins, and regulates cell edge dynamics and focal adhesion assembly in motile epithelial cancer cells via proteins including vimentin, ERC1 (ELKS/RAB6-interacting/CAST family member 1) and β1-integrin." (PMID 30005669, 2018).
infection (4 papers, 2015 to 2026). The state of being infected such as from the introduction of a foreign agent such as serum, vaccine, antigenic substance or organism. "Importantly, ERC1, CDC37, WDR61 and TIPRL showed similar reduction in protein levels during infection with the AD169 virus." (PMID 26599541, 2015).
ERC1 also shares sentences with these, for which no sentence is quoted: neurological diseases (3 papers); epilepsy (2); Intellectual disability (2); Anxiety (1); Cognitive impairment (1); colon adenocarcinoma (1); developmental delay (1); developmental verbal dyspraxia (1); fibrosarcoma (1); genetic disorder (1); gynecologic cancer (1); hydatidiform mole (1); Koolen-de Vries syndrome (1); language disorder (1); lung adenocarcinoma (1); lung carcinoma (1); melanoma (1); Miller-Dieker syndrome (1); Neurodevelopmental delay (1); non-small cell lung carcinoma (1); osteoporosis (1); pancreatic adenocarcinoma (1); pancreatic cancer (1); pancreatic ductal adenocarcinoma (1); pontocerebellar hypoplasia type 2E (1); retinal disorder (1); retinitis pigmentosa (1); Rolandic epilepsy (1); schizophrenia (1); thyroid cancer (1).